LDHA (lactate dehydrogenase A)
Diseases named in the same sentence as LDHA in open-access papers (continued):
Sharing a sentence is not in itself a finding about the gene and the disease.
cancer (continued). "The inhibition of LDHA leads to oxidative stress and subsequent mitochondrion-dependent apoptosis in cancer cells." (PMID 25973606, 2015). "LDHA is elevated and activated in many cancers and is believed to play a crucial role in tumor initiation, maintenance and progression." (PMID 25973606, 2015). "Inhibition of LDHA induces ROS production, decreases cellular ATP levels and inhibits glycolysis, therefore inhibits cell growth and triggers cell death in cancer." (PMID 26121691, 2015). "In cancer cells, LDHA rapidly consumes pyruvate produced by glycolytic pathway, leading to increased aerobic lactate production." (PMID 26121691, 2015). "Cancer cells overexpressed miR-374a has decreased levels of LDHA compared with miR-374a-MUT (rs18407893 at 11p15.4)." (PMID 26062441, 2015). "LDHA upregulation is commonly observed in cancers, and reasons for LDHA upregulation in cancers is varied." (PMID 26062441, 2015). "PFKFB3 and PDHK1 were up-regulated under hypoxic conditions in both cancer cell lines, while Hexokinase II and LDHA were up-regulated only in MCF-7 cells at 0.5% O2." (PMID 26259240, 2015). "Enhanced glucose uptake through GLUT1 and increased aerobic glycolysis through LDHA and PDK1 is the hallmark of cancer cells." (PMID 26484566, 2015). "While lactate produced by LDHA had traditionally been considered as the waste product of glycolysis, recently it has been recognized as a critical regulator that affects cancer progression." (PMID 26506419, 2015). "In most cancers, LDHA is highly expressed and diverts the energy flow from mitochondria to from lactate." (PMID 26378042, 2015). "One protein of particular interest to us as a potential therapeutic anti cancer target is mammalian lactate dehydrogenase A (LDHA)." (PMID 26717415, 2015). "Among the various enzymes and isozymes that catalyze specific reactions in glycolysis, four crucial speed-limiting enzymes, GLUT1, HK2, PKM2, and LDHA favor aerobic glycolysis and growth in certain cancer types." (PMID 26512921, 2015). "HIFs, as well as MYC, are pivotal factors for tumorigenesis in many types of human cancers and are able to activate LDHA." (PMID 24884974, 2014). "This approach would assist in the design and development of better LDHA inhibitors, contributing to the growing efforts that target energy metabolism for cancer therapy." (PMID 24466056, 2014). "LDHA is commonly overexpressed in cancer cells therefore only the LDHA gene product was targeted for knockdown in this study." (PMID 24465604, 2014). "The generation of lactate is critically important to cancer cell metabolism and survival, both of which would be impaired by LDHA inhibition." (PMID 24363178, 2014). "We compared the expression of LDHA protein between 85 matched normal/cancer specimens from the same patients." (PMID 24885701, 2014). "Summarizing in other words, targeting detoxifying systems (e.g. TKTL1, LDHA) make cancer cells or (oral) precursor lesions more vulnerable to apoptosis." (PMID 25048361, 2014). "Higher rate of glycolysis has been long observed in cancer cells, as a vital enzyme in glycolysis, lactate dehydrogenase A (LDH-A) has been shown with great potential as an anti-cancer target." (PMID 25361010, 2014). "Inhibition of LDHA enzymatic activity resulted in profound reduction of lactate production in a variety of cancer cells of different origins." (PMID 24280423, 2013). "Reduction of LDHA levels in cancer cells by siRNA or shRNA stimulates mitochondrial respiration and reduces cellular proliferative and tumorigenic potential both in vitro and in xenograft models." (PMID 24280423, 2013). "Our small-molecule inhibitors allowed us to avoid these problems and to address consequences of rapid chemical inhibition of LDHA in cancer cells." (PMID 24280423, 2013). "In recent years, lactate dehydrogenase A (LDH-A) is emerging as a novel therapeutic target for cancer treatment." (PMID 23457597, 2013).
cancer (continued). "LDHB, when present, is constitutively expressed, whereas LDHA is inducible in hypoxic conditions and often overexpressed in cancers with a MYC amplification." (PMID 24280423, 2013). "These compounds enabled us to explore the consequences of rapid chemical inhibition of LDHA activity in cancer cells." (PMID 24280423, 2013). "Rapid chemical inhibition of LDHA by these quinoline 3-sulfonamids led to profound metabolic alterations and impaired cell survival in carcinoma cells making it a compelling strategy for treating solid tumors that rely on aerobic glycolysis for survival." (PMID 24280423, 2013). "Similar to cancer cells, lal−/− bone marrow MDSCs showed increased gene expression of both lactate dehydrogenase A and B, which keep pyruvate away from the mitochondria." (PMID 22383970, 2012). "Knocking down or chemically inhibiting LDHA or PDK in various cancers shifts metabolism from glycolysis and lactate production to mitochondrial respiration, with an associated increase in mitochondrial ROS production and induction of apoptosis." (PMID 21541279, 2011). "Furthermore, after NIR-PIT, multiplex IHC demonstrated the release of LDHA, which was localized in the cytoplasm of cancer cells in the control group, suggesting necrotic cell death." (PMID 39751657, 2025). "Given LDHB’s emerging role in cancer metabolism, particularly in tissues with high oxidative demands or in tumors that switch from LDHA to LDHB expression, selective LDHB inhibition may provide unique therapeutic advantages." (PMID 40733189, 2025). "In our recent study, 1,6-hexanediol (1,6-HD) has emerged as a compound of interest due to its inhibitory activity on enzymes crucial for glycolysis, such as lactate dehydrogenase A (LDHA), the major player for ATP production in the Warburg effect of cancer cells." (PMID 39836351, 2025). "Moreover, LDHA knockdown attenuates the progression of CSCs and drug-resistant cancer phenotypes driven by oncogenic KRAS and/or EGFR signaling pathways." (PMID 41368023, 2025). "Knocking down Dio3os or PTBP1 led to a shift to unstable LDHA variants, emphasizing the Dio3os-PTBP1 interaction's role in maintaining LDHA mRNA stability through 3'UTR integrity and thereby enhancing glycolysis in drug-resistant cancer cells." (PMID 41235096, 2025). "While cancer cells overexpress lactate dehydrogenase A (LDHA) to support glycolytic flux and lactate production, the role of LDHB-which preferentially catalyzes lactate oxidation-remains unclear." (PMID 40940446, 2025). "Combining lactate metabolism inhibitors, such as LDHA inhibitors, with traditional cancer treatments may enhance treatment effectiveness and reduce the development of resistance." (PMID 41179284, 2025). "Notably, lactylation of NBS1 enhances DNA damage repair and promotes chemoresistance, contributing to poor prognosis in cancer patients, with LDHA playing a central enzymatic role in this process." (PMID 41152975, 2025). "LDHA is upregulated in BC and promotes the proliferation, migration, and invasion of cancer cells." (PMID 40849487, 2025). "Taken together, LDHA may increase lactate production to activate the signaling pathways which critical for cancer stemness, such as NF-κB, IL-8 and HIF-1α, and further regulate the CSC properties." (PMID 39930542, 2025). "Notably, oxidative cancer cells (cancers that rely on mitochondrial oxidative phosphorylation) are less vulnerable to LDHA inhibitors." (PMID 40956032, 2025). "Lactate dehydrogenase A (LDHA) can regulate tumorigenesis and cancer progression." (PMID 39930542, 2025). "Notably, macrophages have been shown to express HIF-1α, which requires LDHA activity in cancer cells." (PMID 40746883, 2025). "LDHA is the prevailing isoform utilized by cancer cells to bypass OXPHOS." (PMID 39934144, 2025). "In addition, EGCG inhibits lactate dehydrogenase A (LDHA), a key enzyme involved in cancer cell glycolysis, leading to reduced lactate production, glucose consumption, and glycolytic activity." (PMID 40918466, 2025).
cancer (continued). "However, in cancer cells, pyruvate is predominantly converted to lactate by lactate dehydrogenase A (LDHA), facilitating rapid ATP production and regeneration of NAD+, essential for sustaining high glycolytic flux." (PMID 40723225, 2025). "Targeting LDHA inhibition effectively suppresses cancer cell growth." (PMID 41561760, 2025). "Furthermore, in vivo NIR-PIT showed histological signs of cancer cell damage, such as cytoplasmic vacuolation, nuclear dysmorphism, and extracellular leakage of LDHA consistent with cell death." (PMID 39751657, 2025). "This dual role makes LDHA an attractive therapeutic target: inhibiting LDHA could simultaneously disrupt the cancer cell’s metabolic fuel and erase “pro-resistance” epigenetic marks." (PMID 41422325, 2025). "Therefore, we aim to demonstrate the functions and regulatory mechanisms of LDHA on cancer stem cell (CSC) properties and gemcitabine resistance in PDAC." (PMID 39930542, 2025). "LDHA expression is known to be transactivated by HIF-1, and elevated LDHA expression is positively associated with HIF-1 expression and worse survival outcomes in cancer patients." (PMID 39930542, 2025). "However, in human cancers, the role of LDHA in prognosis and immunotherapy hasn’t been investigated." (PMID 38709280, 2024). "This article focuses on identifying whether LDHA can be a potential marker of cancer, which is important for future clinical treatment of tumors and efficacy monitoring." (PMID 38709280, 2024). "In conclusion, LDHA from derived from LM.SIG might serve as a prognostic pan-cancer biomarker that also predicts immunotherapy response." (PMID 38664705, 2024). "The effect of ETV in apoptosis induction through the inhibition of CK1ε and the potential effect of DRV against LDHA that affects several of the other hallmarks of cancer can be working in tandem to make the combination of these drugs especially effective at 48 h time points." (PMID 38540260, 2024). "Elevated LDHA activity promotes the proliferation and invasiveness of cancer cells." (PMID 38704368, 2024). "Additionally, we also evaluated the potential contribution of LDHA to drug resistance for immunotherapy of cancers." (PMID 38709280, 2024). "Consequently, Mn-CuS@BSA-FA emerges as a NIR-responsive glycolytic inhibitor, with potential applications in cancer therapy, due to its ability to suppress cellular ATP levels, LDHA activity, and HIF-1α expression." (PMID 39479443, 2024). "Our results are similar to those reported in other cancers, and suggested that LDHA could promote malignant biological behavior of EC cells." (PMID 39582531, 2024). "LDHA, another rate-limiting enzyme for glycolysis, contributes to immune escape through the regulation of lactate production, promoting cell proliferation, and is highly expressed in various types of cancer." (PMID 38744310, 2024). "In addition, FX11, a selective inhibitor of LDHA, was observed to inhibit the proliferation of cancer cells and exert antitumor activity in a mouse transplantation tumor model." (PMID 39502530, 2024). "Therefore, the disruption of glycolytic progression by inhibiting the activity of key glycolytic regulatory enzymes, including pyruvate kinase M2 (PKM2) and lactate dehydrogenase A (LDHA), has become a novel direction in the development of anti-cancer drugs." (PMID 38474453, 2024). "Generally, PDK4 and LDHA collaborate to enhance the glycolysis of cancer cells." (PMID 38200513, 2024). "Many human cancers show higher LDHA levels than those in normal tissues." (PMID 38725063, 2024). "Targeting key components of glycolysis, such as hexokinase 2 (HK2) and lactate dehydrogenase A (LDHA), with inhibitors could potentially selectively eliminate cancer cells." (PMID 38479191, 2024). "Similar to PKM2, the regulation of LDHA is critical in cancer cells." (PMID 38773429, 2024). "Besides, we also accessed the prognostic significance of LDHA expression in disease-free survival (DFS) for pan-cancer in thirty-three cancer types." (PMID 38709280, 2024).
cancer (continued). "Previous studies have shown that LDHA expression is elevated in most types of cancer cells." (PMID 39680520, 2024). "In line with these in vitro experiments, we found that besides Ang-2 expressing endothelial cells, brain metastatic human cancer cells in the pre-metastatic niche strongly expressed lactate dehydrogenase A (LDHA), a surrogate enzyme for a metabolic deficiency state." (PMID 38831719, 2024). "In addition, in gastric cancer, where an overexpression of LDHA has been confirmed, sodium oxamate was observed to decrease lactate production, resulting in a dose-dependent inhibition of cancer cell proliferation in the presence of glucose." (PMID 38731601, 2024). "Furthermore, c‐Myc and HIF‐1 have been shown to cooperatively enhance LDHA transcription in cancer cells." (PMID 39021353, 2024). "Additionally, elevated LDHA in bladder cancer is correlated with cancer proliferation and metastasis." (PMID 39107723, 2024). "In recent years, some specific compounds, including phthalimide, dibenzofuran derivatives and 1-(phenylseleno)-4-(trifluoromethyl) benzene, were shown to function as LDHA inhibitors and displayed the inhibition of the development and multiplication of cancer cells." (PMID 39502530, 2024). "Therefore, we further analyzed that the correlation of LDHA expression with the sensitivity of 60 human cancer cell lines (NCI-60) to more than 200 chemotherapeutic drugs." (PMID 38709280, 2024). "CircRNAs also affect the glycolytic phenotype of cancer cells by regulating LDHA transcription." (PMID 37190158, 2023). "Additionally, lactate dehydrogenase A (LDHA) is one of the key enzymes in glycolysis progress which have crucial effects on cancer cell growth." (PMID 37925501, 2023). "For instance, LDHA, an isoenzyme of lactate dehydrogenase that functions in the final step of glycolysis to convert pyruvate to lactate, has been demonstrated to be elevated in tumors and can be used as a prognostic marker in cancer patients." (PMID 37843550, 2023). "PSTMB, a small molecule, suppressed the activity of LDHA and lactate production in cancer cells." (PMID 36984785, 2023). "CircRNA affects cancer glucose metabolism by regulating LDHA." (PMID 37599427, 2023). "In addition, the results of CytoTRACE showed that LDHA is highly correlated with inferred cancer stemness at the single-cell level, and we verified the correlation at the bulk-tissue level using the TCGA cohort." (PMID 37795453, 2023). "Inhibition of LDHA, therefore, may limit the energy supply in tumors, reducing cancer cells' ability to spread and invade." (PMID 36583135, 2023). "Thus, LDHA can guarantee the metabolic flexibility of cancer cells, allowing them to adjust to challenging conditions." (PMID 37965333, 2023). "For example, PKM and LDHA are related to central carbon metabolism in cancer." (PMID 37124724, 2023). "However, in cancer cells, pyruvate is instead converted into lactate, a process facilitated by lactate dehydrogenase A (LDHA)." (PMID 37345116, 2023). "Acetylation and succinylation of LDHA may play opposite roles in the regulation of LDHA level in cancer." (PMID 35278714, 2023). "Besides, we found LDHA also promoted cancer progression through being involved in the cell cycle and DNA replication." (PMID 37925501, 2023). "Further, HSF1 involves multiple layers of cellular regulations to promote malignant phenotypes in cancer cells, including increasing glycolysis to overcome therapy resistance via lactate dehydrogenase A (LDH-A) and promoting autophagy to enhance cell survival via autophagy-related protein 7 (ATG7)." (PMID 37958341, 2023). "LDHA, which is increased in hematological malignancies and solid cancers, encodes the M-subunit of lactate dehydrogenase (LDH), which regulates aerobic glycolysis to fulfill the energy and biosynthetic demands of malignant tumors." (PMID 37728418, 2023).
cancer (continued). "LDHA, an isoenzyme of lactate dehydrogenase, functions in the final step of glycolysis to convert pyruvate to lactate, and was reported to be up-regulated in tumors and as a marker of prognosis of cancer patients." (PMID 36732657, 2023). "Furthermore, LDHA inhibition increases the sensitivity of resistant cancer cells to chemotherapy and radiation therapy." (PMID 37853052, 2023). "Furthermore, through functional enrichment analysis, we found a significant correlation between four signature genes (CBX2, LDHA, SPP1, and ZC4H2) and malignant tumor biology, exhibiting upregulation in high-risk patients." (PMID 37287752, 2023). "LDHA inhibition by oxamate resulted in the accumulation of reactive oxygen species (ROS) and depletion of adenosine triphosphate (ATP), leading to increased sensitivity to radiotherapy in A549 and H1975 cancer cells." (PMID 37915411, 2023). "Notably, there are some potential challenges during the application of LDHA inhibitors for cancer treatment." (PMID 37965331, 2023). "LDHA depletion in cancer cells reduces CAF levels in the PDAC TME." (PMID 37733442, 2023). "The mechanism could be explained by the increased lactate levels in cancer cells resulting from the increased LDHA activity, which promotes cancer cell growth." (PMID 35278714, 2023). "LDHA positively regulated the cell cycle, DNA replication, mismatch repair, protein export, base excision repair, RNA degradation, pathways in cancer and retinoic acid-inducible gene I (RIG-I) like receptor signaling pathway, but negatively regulated oxidative phosphorylation." (PMID 37925501, 2023). "LDHA is highly expressed in many malignant tumors, as well as in GBMs." (PMID 37298317, 2023). "LDHA inhibition reduced the growth and viability of cancer cells through hampering ATP production in glycolysis process, which was considered a suitable target for cancer therapy." (PMID 37770937, 2023). "LDHA shows a high expression profile and activated status in many cancers." (PMID 35278714, 2023). "Therefore, LDHA phosphorylation is emerging as a potential drug target to disrupt cancer progression." (PMID 37480145, 2023). "However, related studies have found that silencing the LDHA gene can reduce ATP production, inhibit cell growth, decrease invasiveness, and induce oxidative stress and radiosensitivity in cancer cells." (PMID 36811010, 2023). "In the current study, we found there was a close correlation between LDHA and LDHB expression levels and multiple TIIC subsets, i.e., B cells, cancer-associated fibroblast, CD4+ T cells, CD8+ T cells, endothelial cells, and neutrophils, and massive immunoinhibitors such as VTCN1." (PMID 37547725, 2023). "One of that isoenzymes is LDHA, which can be increased in most cancers." (PMID 35990198, 2022). "LDHA is almost universally upregulated in cancer cells by c-Myc and HIF-1α." (PMID 36531060, 2022). "In addition to MCM2 to MCM7, six downstream oncogenic targets of c-MYC implicated in cancer survival and metabolism including PSMA1, PSMA6, PSMB2, HDAC2, LDHA and SPRING were positively correlated with IFITM3 in 71 GC specimens using the Cho dataset." (PMID 35941699, 2022). "In addition, miR-30d-5p was overexpressed by targeting LDHA to reduce glycolysis in malignant tumors, and thus inhibited cancer development." (PMID 35155437, 2022). "Cancer cells in which the Warburg effect occurs show dissociation of FLCN from LDHA." (PMID 35457153, 2022). "Notably, several cancer‐related pathways that contain the lactate dehydrogenase A (LDHA) gene were enriched, including the hypoxia‐inducible factor (HIF) pathway, the HIF‐1α transcription factor network, and the lactate fermentation pathway." (PMID 36307872, 2022). "Furthermore, the genetic or pharmacological inhibition of LDHA suppresses cancer growth, demonstrating a cancer-promoting role for this enzyme." (PMID 35982980, 2022). "Hence, LDHA or LDH5 often attracts medicinal chemists’ attention as the target to regulate cancer metabolism." (PMID 36247675, 2022).